PPARA (peroxisome proliferator activated receptor alpha)
Diseases named in the same sentence as PPARA in open-access papers (continued):
Sharing a sentence is not in itself a finding about the gene and the disease.
liver disease (continued). "We hypothesize that activation of PPARα can be therapeutically leveraged to overcome gut-liver axis dysregulation for resolution of liver disease." (PMID 40793786, 2025). "PPARα, which is primarily expressed in the liver and skeletal muscle, promotes fatty acid oxidation and lipid clearance while controlling inflammation, making it a target for treating cardiovascular and liver diseases." (PMID 40926269, 2025). "However, PPARα agonists have failed in clinical trials in patients with liver disease, highlighting the challenge of translating findings from animal models to human diseases." (PMID 41159141, 2025). "PPARα levels decrease during alcoholic liver disease and non‐alcoholic steatohepatitis, which makes it a potential therapeutic biomarker for metabolism‐related liver diseases." (PMID 38652093, 2024). "PPARα is downregulated in many liver diseases such as NAFLD and NASH." (PMID 38633246, 2024). "This is in line with reports on altered hepatic PPARα expression in liver diseases." (PMID 36139455, 2022). "Our research also illustrates FXR and PPARα may be potential drug targets for liver diseases since they can regulate Lgr5+ cells fate." (PMID 36168631, 2022). "The role of PPARα has been clarified in several liver diseases." (PMID 22645601, 2012). "The regulation of PPARα by E6-AP may provide a basis for HCV-inducedprogression of liver disease, and is worthy of investigation." (PMID 19107217, 2008). "Thus, we speculate that the molecular interaction between NF-kB and PPARα in liver may be potentially therapeutic targets for the treatment of hepatic diseases." (PMID 36678298, 2023). "Suppression of the PPARα/RXRα pathway by miRNAs may thus promote the progression of liver disease." (PMID 26733244, 2016). "With excessive alcohol consumption, PPARα gene transcription is inhibited through still unknown mechanisms and may contribute, through an increased oxidative stress and inflammatory response, to the wide spectrum of liver disorders observed with alcoholism." (PMID 23024649, 2012). "More importantly, signaling pathways such as Nrf2, NF-κB, PI3K/Akt/mTOR, NLRP3, Wnt/β-catenin, TGF-β1/Smad3, AMPK/SREBP, PPARα/γ, MAPKs, and Caspases are identified as key targets through which API exerts its beneficial effects in various liver diseases." (PMID 39749193, 2024). "This will lead to considerations of PPARα as a better molecular target, alone or in combination with other PPAR factors, in the treatment of NASH and other liver inflammatory diseases." (PMID 35625520, 2022). "Notably, fenofibrate, a PPARα agonist, was found to increase FAO and attenuate cystic kidney and liver disease in Pkd1RC/RC mice." (PMID 39000280, 2024). "This multifactorial improvement of liver disease noted when combining both drugs suggests that a course of treatment that includes both reduced FSP27 activity and activation of PPARα could provide therapeutic benefit to patients with NAFLD/NASH." (PMID 28874443, 2017). "Hepatocyte fatty acid accumulation occurs in the absence of PPARα in the liver, leading to reduced levels of proteins and enzyme genes involved in fatty acid metabolism (such as ACSL1), thereby initiating and progressing liver disease." (PMID 39947476, 2025).
liver cancer (77 papers, 2002 to 2025). An epithelial or non-epithelial malignant neoplasm that arises from the liver. "Studies using Ppara-null and PPARA-humanized mice demonstrated an essential role for PPARα in rodent liver cancer caused by PPARα ligands." (PMID 37623879, 2023). "Recent studies have shown that PPARα-deficient mice are remarkably sensitive to DEN(diethylnitrosamine)-induced liver cancer, and PPARα inhibits HCC development by mediating the NF-κB pathway." (PMID 35280774, 2022). "Long-term administration of PPARα agonists was reported as early as 1980 to cause liver cancer in rodents." (PMID 36611922, 2022). "It is unclear, however, how PPARα and other factors are associated with metabolic changes in liver cancer tissues, and the question of the kinds of changes that occur in energy metabolism as liver cells become cancerous is one of great interest." (PMID 22168458, 2011). "This mode of action is supported by the observation that even a one year exposure to PPARα agonists was insufficient to cause an increase in the incidence of hepatic neoplasms in PPARα knock-out mice." (PMID 17118139, 2006). "Based on the Ingenuity Pathway Analysis, 11 genes associated with liver cancer development were up-regulated by at least two PPARα agonists tested." (PMID 17118139, 2006). "Exposure to agonists of peroxisome proliferator-activated receptor alpha (PPARα) causes liver cancer in rodents, with aged animals being more susceptible than their younger counterparts to this effect." (PMID 12805935, 2002). "Chronic ligand activation of PPARα causes liver cancer in rodents." (PMID 37623879, 2023). "Long-term administration of PPARα agonists causes liver cancer in rodents." (PMID 27658584, 2016). "Although the strong hepatocyte proliferative effect of rodent PPARα causes liver cancer, such effective proliferative effect may be beneficial for liver regeneration." (PMID 25991671, 2015). "Furthermore, long-term administration of PPARα agonists caused liver cancer in rodents, and Pparα-null mice were resistant to the hepatocarcinogenic effects of PPARα agonists." (PMID 23951092, 2013). "However, in a PPARα humanized model, sustained PPARα activation very rarely provoked liver cancers, which suggests that structural differences between human and mouse PPARα are responsible for the differential susceptibility to peroxisome proliferator-induced hepatocarcinogenesis." (PMID 35954274, 2022). "In gastric cancer, miR-665 and miR-760 targeted CD44 and ASGR2; in liver cancer, miR-638 showed broad predictions (e.g., HO-1, PPARα/γ)." (PMID 41378310, 2025). "PPARα plays a significant role in the development and progression of liver cancer by controlling lipid metabolism, glucose regulation, and inflammation in the liver cells." (PMID 41378310, 2025). "A comprehensive study, integrating TCGA datasets, clinical samples, and both in vivo and in vitro experiments, suggests that ACOX2 impedes the progression of liver cancer through the PPARα pathway." (PMID 38279987, 2024). "L. plantarum hydroxy fatty acids reduce SREBP-1c mRNA expression and LXRα activation, which is the proposed mechanism by which L. plantarum suppresses lipogenesis and triacylglycerol accumulation in HepG2 liver cancer cells that express low levels of PPARα." (PMID 38601738, 2024). "By activating the stearoyl-CoA desaturase 1 pathway, the activated PPARα was significantly upregulated for the maintenance of CSC stemness in human liver cancer." (PMID 37251321, 2023). "Increases in oxidative stress and associated indirect DNA damage are thought to play a role in the PPARα mediated liver cancer mode of action (MOA)." (PMID 38133364, 2023). "Diminished liver carcinogenesis has also been observed in PPARA-humanized mice after chronic administration of PPARα agonists demonstrating the mechanism of species differences in liver cancer between rodents and humans." (PMID 37623879, 2023).
liver cancer (continued). "For example, liver-CASs were enriched with motifs of HNF4a and PPARa, which are vital TFs for the development of liver cancer." (PMID 37283809, 2023). "In conclusion, we demonstrated a PRG ACOX2, and its overexpression reduced the proliferation and metastasis of liver cancer in vitro and in vivo through PPARα pathway." (PMID 33414412, 2021). "Clofibrate is an exogenous ligand of peroxisome proliferator-activated receptor alpha (PPARα), and it is suggested that clofibrate generates reactive oxygen species through PPARα and induces liver cancer in rats." (PMID 34503583, 2021). "Next, we examined the relationship of C/EBPα, PPARα, and gankyrin expression in liver cancer tissues using QRT-PCR." (PMID 29636686, 2018). "In contrast, the C/EBPα and PPARα mRNA levels were both lower in liver cancer tissues compared to normal tissues." (PMID 29636686, 2018). "For example, PPARα shows duality in liver cancer; low amounts of PPARα activation increase cell apoptosis by changing the tumor microenvironment, and continued high levels of PPARα activation promote the growth of hepatoma carcinoma cells." (PMID 27482818, 2016). "Chronic activation of PPARα in rodents increases liver cancer incidence, whereas suppression of PPARα activity leads to hepatocellular steatosis." (PMID 25689681, 2015). "To further evaluate these findings, we examined the effects of PPARA inhibition on liver cancer cells." (PMID 26206264, 2015). "This study strengthens our understanding of how PPARα mediates hepatocytes proliferation in HCC and provides new mechanistic insights into the importance of PPARα in inhibiting liver cancer development; one such key pathway is via suppressing NF-κB activation." (PMID 25327562, 2014). "Several reports describe PPARα agonists conferring inhibitory effects on cancer cell lines and animal models colorectal cancer, ovarian cancer and liver cancer in a PPARα-dependent manner." (PMID 25327562, 2014). "Increased hepatocellular replication has been advanced as an important factor in liver cancer induced by PPARα agonists in rodents." (PMID 17129391, 2006). "Several studies have used PPARα knockout mice to try to determine specific responses associated with PPAR agonism and potential MOA of liver cancer induction, but concerns have been raised regarding the adequacy of this model." (PMID 16966106, 2006). "In addition, FABP1, HO-1, LXR-α, PPAR-alpha (PPARα), and PPARγ have been affected by MPs in liver cancer cells." (PMID 41378310, 2025). "Furthermore, CD147 reprograms fatty acid metabolism in liver cancer cells through the Akt/mTOR/SREBP1c and P38/PPARα pathways, further underscoring the critical role of lipid metabolism in liver cancer." (PMID 41262444, 2025). "However, Ppara-null mice are resistant to PPARα agonists-induced liver cancer demonstrating that PPARα mediates hepatocarcinogenesis resulting from exposure to these non-genotoxic rodent carcinogens." (PMID 37623879, 2023). "KRT23 is PPARA dependent and also highly expressed in human liver cancer." (PMID 36796223, 2023). "Further, the expression of PPARA is positively correlated with ACOX2 in liver cancer." (PMID 33414412, 2021). "Moreover, it was confirmed that the expression levels of PPARα, PPARγ, FABP1, FABP4, and FABP5 were downregulated in GL22-treated xenograft tumors, which indicates that PPAR-FABPs signaling pathway exerts a significant anticancer effect against liver cancer." (PMID 34771120, 2021). "The effect of PPARα activation is the opposite in the liver cancer, PPARα activation enhanced the expression of MYC, which in turn enhanced the expression of the Krt23, a downstream target gene of the PPARα, thereby promoted the proliferation of the liver cancer cells." (PMID 33132907, 2020).
liver cancer (continued). "Moreover, the expression levels of PPARα, PPARγ, FABP1, FABP4, and FABP5 were downregulated in GL22-treated xenograft tumors, indicating that GL22 exerted a significant anticancer effect against liver cancer in vivo mediated by PPAR–FABPs signaling pathway." (PMID 29880886, 2018). "PPARα is also involved in the growth and proliferation of liver cancer cell lines." (PMID 29636686, 2018). "PPARα was suggested to promote the expression of let-7 and miR-200c in hepatic cancer cells." (PMID 28167956, 2017). "Another point implicating retrotransposition in the observed tumorigenicity is that while PPARα activators are tumorigenic in rodents, they have been deemed of limited to no risk for liver cancer in humans." (PMID 28472135, 2017). "Future efforts could focus on determining linkages between activation of PPARα and downstream events including lipid metabolism, cell fate and under long-term activation conditions, liver cancer." (PMID 25689681, 2015). "Thus, this is the first in vivo evidence for an essential role of PPARα in primary liver cancer development." (PMID 25327562, 2014). "Second, formation of HCC was shown to depend on peroxisome proliferator-activated receptor alpha (PPARα) transcription factor, which has been implicated in occurrence of non-virus induced liver cancer." (PMID 23358390, 2013). "From carcinogenesis experiments using mice it is well known that PPARα is necessary for development of liver cancer induced by peroxisome proliferators, and the relationship between PPARα and the development of liver cancer has been the focus of considerable attention." (PMID 22168458, 2011). "On the other hand, mouse carcinogenicity studies showed that PPARα is necessary for the development of liver cancer induced by peroxisome proliferators, and the relationship between PPARα and the development of liver cancer have been the focus of considerable attention." (PMID 22168458, 2011). "Activation of PPARα reportedly contributes to the carcinogenesis process for liver cancer, and the results of this study indicate the possibility that this may also hold true for humans." (PMID 22168458, 2011). "Chronictreatment with PPARα agonist results in an increased incidence of liver tumorswhich were thought to have occurred through a PPARα-mediated mechanism asrevealed by the resistance of PPARα-null mice to liver cancer induced byWy-14,643 exposure for 11 months." (PMID 18769559, 2008). "Treatment of rodents with agonists of PPARα results in liver cancer via mechanisms that remain unclear." (PMID 17129391, 2006). "For these reasons, the present studies were designed to test the hypothesis that alterations in hepatic lipid metabolism cause liver cancer independent of PPARα." (PMID 37623879, 2023). "So, ACOX2 may regulate the PPARα pathway to inhibit the proliferation of liver cancer." (PMID 33414412, 2021). "However, due to species differences at the molecular level of PPARα regulation, humans might be resistant to liver cancer induced by PPARα agonists." (PMID 25198467, 2014). "However, as is often pointed out, increases in peroxisome proliferation and incidence of HCC have not been demonstrated in patients who take peroxisome proliferators long term, so we cannot say with certainty that PPARα contributes to the development of liver cancer in humans." (PMID 22168458, 2011). "In liver cancer, PMMA upregulated HO-1 and downregulated PPARα/FABP1, suggesting oxidative stress and lipid dysregulation." (PMID 41378310, 2025). "The identified connections with key lipid/triglyceride metabolism biomarkers, namely PPARA, APOC3, and APOA5, suggest the involvement of SELENOP in lipid homeostasis within the context of liver cancer." (PMID 39001444, 2024). "To further validate the miR-9/PPARA interaction, we examined PDK4 expression levels after miR-9 overexpression in liver cancer cells." (PMID 26206264, 2015).
liver cancer (continued). "Taken together, our study identified a novel microRNA signaling pathway, consisting of miR-9, PPARA and CDH1 that is deregulated in HCC patients affecting liver cancer cellular invasiveness." (PMID 26206264, 2015). "Althoughrodents are the only species in which activation of PPARα promotes liver cancer, for a long timeit was thought that Di(2-ethylhexyl)phthalate (DEHP), a commonly usedindustrial plasticizer, might cause liver tumorigenesis presumably viaactivation of PPARα." (PMID 18725983, 2008). "While we observed robust PPARα target gene induction previously with DCA treatment after 6 days, general consensus is DCA does not lead to liver cancer through a PPAR-mediated pathway." (PMID 38764585, 2024). "Activation of mouse, but not human, PPARα induces hepatocellular proliferation, hepatomegaly, and liver cancer." (PMID 25991671, 2015). "There have been no reports, however, demonstrating that PPARα is involved in the development of human liver cancer." (PMID 22168458, 2011). "While there is strong evidence that PPARα is required to mediate liver carcinogenesis caused by chronic ligand activation of PPARα in rodents, there is equally convincing evidence that humans do not develop liver cancer following administration of PPARα agonists." (PMID 37623879, 2023). "In liver cancer cells, miR-200c is activated by nuclear receptors PPARα (peroxisome proliferator activated receptor alpha) and LRH-1 (liver receptor homolog-1), and is inhibited by SHP (small heterodimer partner), a transcriptional repressor that interacts with PPARα and LRH-1." (PMID 34884985, 2021). "Also, PPARα and ACOX2 are strongly correlated in the liver cancer tissues." (PMID 33414412, 2021). "GSEA enrichment analysis results for high and low expression of PPARα and NR1H4 in BA patients, and GSEA results excluding patients with hepatitis B, normal liver, liver cancer, and non-BA cholestasis." (PMID 36090996, 2022).